HOTAIR (HOX transcript antisense RNA)
Diseases named in the same sentence as HOTAIR in open-access papers (continued):
Sharing a sentence is not in itself a finding about the gene and the disease.
gastric cancer (continued). "In our meta-analysis, we found that in gastric cancer, HOTAIR expression was significantly associated with lymph node metastasis and vessel invasion without heterogeneity." (PMID 25157956, 2014). "In gastric cancer, HOTAIR expression was found to be significantly associated with lymph node metastases (present vs. absent: OR 4.47, 95% CI: 1.88–10.63) and vessel invasion (positive vs. negative: OR 2.88, 95% CI: 1.38–6.04) without obvious heterogeneity." (PMID 25157956, 2014). "We also identified the function of HOTAIR in gastric carcinoma cells by applying gain- and loss-of-function approaches." (PMID 24775712, 2014). "On the other hand, a significant association was found between HOTAIR expression and lymph node metastasis (P= 0.043), venous infiltration (P=0.0083), and short overall survival (P=0.018) in the diffuse type gastric cancer." (PMID 24130837, 2013). "The association of HOTAIR expression with clinicopathological features in intestinal type of gastric cancer." (PMID 24130837, 2013). "It was reported that the functional effect of the HOTAIR rs920778 SNP T variant allele was to promote enhancer activity and expression of HOTAIR in esophageal squamous cell carcinoma cells, gastric cancer, and cervical cancer cells as well as in tissues of these cancer types in a Chinese population." (PMID 30813594, 2019). "Moreover, HOTAIR is notably elevated in gastric cancer, where it is associated with tumor invasion, metastases, and poor outcomes." (PMID 28649178, 2017). "In conclusion, our results indicate that HOTAIR polymorphism rs920778 is more generally associated with cancer risk, particularly in Asians, whereas polymorphism rs4759314 may be a risk factor for gastric cancer." (PMID 27246974, 2016). "Moreover, there is an allelic regulation of rs920778 on lncRNA HOTAIR expression via this enhancer in both ESCC and gastric cancer, with higher HOTAIR expression among T allele carriers." (PMID 27549736, 2016). "In this study, we conducted a two-stage case-control study to evaluate whether genetic variations of HOTAIR were associated with gastric cancer risk." (PMID 26384301, 2015). "All these indicated that HOTAIR and its genetic variations may be a potential biomarker for risk assessment, early detection and therapeutic target of gastric cancer; and larger prospective and experimental studies were warranted to further validation." (PMID 26384301, 2015). "HOTAIR upregulation was associated with larger tumor size, advanced pathological stage and extensive metastasis, and also correlated with shorter overall survival of gastric cancer, endometrial cancer, lung cancer, renal cell carcinoma (RCC) patients." (PMID 26172293, 2015). "Furthermore, IHC and qRT-PCR assays revealed that HER2 was mainly upregulated in advanced stage gastric cancer tissues or those with lymph node metastasis, and associated with high HOTAIR expression." (PMID 24775712, 2014). "HOTAIR upregulation was associated with larger tumor size, advanced pathological stage and extensive metastasis, and also correlated with shorter overall survival of gastric cancer patients." (PMID 24775712, 2014). "In addition, HOTAIR expression caused more metastases to the liver and other organs, and a defect of HOTAIR suppressed the peritoneal dissemination of gastric carcinoma cells." (PMID 24130837, 2013). "Being experimentally validated particular RNA-DNA interactions may contribute to understanding the mechanisms of human diseases, since, for example, MEG3 and HOTAIR are associated with various cancers (gastric cancer, hepatocellular carcinoma, cervical cancer, etc.)." (PMID 32012884, 2020). "However, little is known about the association of HOTAIR with gastric cancer." (PMID 24130837, 2013). "Several lncRNAs, including GAPLIN, GClnc1, HOTAIR, H19 and MEG, have been identified as being strongly associated with gastric cancer." (PMID 40362520, 2025).
gastric cancer (continued). "Retraction: Jun Xiao, Hao Lai, Sheng-Hong Wei, Zai-Sheng Ye, Fu-Sheng Gong, Lu-Chuan Chen (2019), lncRNA HOTAIR promotes gastric cancer proliferation and metastasis via targeting miR-126 to active CXCR4 and RhoA signaling pathway." (PMID 38695659, 2024). "HOTAIR has been described as being overexpressed in gastric cancer, playing a pivotal role in metastasis and survival." (PMID 38542354, 2024). "Building on the strong base of ncRNA research in localized as well as metastatic solid cancer, one of the first studies analyzed two well-known long non-coding RNAs (lncRNAs), MALAT1 and HOTAIR, in gastric cancer patients." (PMID 39272819, 2024). "In gastric cancer, HOTAIR expression is upregulated to promote the proliferation of gastric cancer cells." (PMID 36816362, 2023). "In this regard, HOTAIR/Mex3b promotes gastric cancer tumorigenesis by inhibiting the RUNX3–Claudin1 tumor suppressive axis." (PMID 36899853, 2023). "For example, the well-known lncRNA HOTAIR acts as a competitive endogenous RNA (ceRNA) for miR-331-3p to regulate the expression of HER2 in gastric cancer." (PMID 35579449, 2022). "The results of our study demonstrated that the five-lncRNAs PART1, UCA1, DIRC3, HOTAIR, and HOXA11AS require more investigation to be confirmed as diagnostic biomarkers in gastric cancer." (PMID 35949302, 2022). "For example, HOTAIR can inhibit the resistance of gastric cancer cells to cisplatin by inhibiting miR-34a to regulate PI3K/Akt and Wnt/−catenin signaling pathways." (PMID 35093153, 2022). "It was observed that the higher expression of HOTAIR promoted gastric-cancer cell proliferation, enhanced the transition of cell cycle G1/S, as well as decreased cancer cell apoptosis by activating WNT/β-Catenin signaling." (PMID 36359888, 2022). "In gastric cancer, HOTAIR was seen to be majorly regulated in cisplatin-resistant gastric cancer cells and tissues." (PMID 36359888, 2022). "Upon analyzing the correlation between HOTAIR and miRNA‐206 in gastric cancer tissues, the results revealed that HOTAIR was negatively correlated with miRNA‐206 (r = −.6557, p < .0001)." (PMID 33473276, 2021). "In the diagnosis of gastric cancer, pancreatic cancer, and colorectal cancer, the expression of HOTAIR is used to distinguish benign and malignant tissues, compared with benign tissues, the expression of HOTAIR in tumor tissues is higher." (PMID 34322392, 2021). "HOTAIR has been found to be upregulated in gastric cancer, and can promote tumor metastasis by binding to EZH2 with the E-cadherin promoter." (PMID 34422902, 2021). "HOTAIR overexpression is strongly associated not only with migration, invasion, and metastasis, but also with the EMT mechanism in gastric cancer both in vitro and in vivo." (PMID 33540611, 2021). "The purpose of this study is to observe the expression of HOTAIR in gastric tissues and its effect on the biological activity of gastric cancer cells through miRNA." (PMID 33473276, 2021). "Related research has proven the high expression of HOTAIR in gastric cancer compared with that in normal tissues." (PMID 33473276, 2021). "In gastric cancer cells, the potential microRNAs binding sites of HOTAIR have been predicted by the computer algorithm miRanda and by combined RegRNA and microRNA.org-target program." (PMID 33540611, 2021). "HOTAIR inhibits cisplatin resistance of gastric cancer cells through inhibition of the PI3K/Akt and Wnt/β-catenin signaling pathways." (PMID 34405017, 2021). "For example, HOTAIR can bind to miR-130a, reducing miR-130a levels in gallbladder cancer, and HOTAIR expression was also inversely related with miR-124 levels in gastric cancer." (PMID 33809601, 2021). "The oncogenic HOTAIR/miR-331-3p/HER2 axis is associated with tumor progression and poor prognosis in gastric cancer." (PMID 33750326, 2021).
gastric cancer (continued). "With respect to gastric cancer, there was a highly expressed HOTAIR in tumor tissues that was found to be strongly correlated with clinical manifestations of those patients such as vascular invasion, lymph node metastasis (LNM), and survival." (PMID 33473276, 2021). "HOX transcript antisense RNA gene (HOTAIR) is a long non-coding RNA which is well-known as an oncogene involved in various cancers, such as lung, breast, colorectal, and gastric cancer." (PMID 34064346, 2021). "In gastrointestinal tract tumors, HOTAIR upregulation appears as an important marker in colorectal cancer and gastric cancer, showing a strong relation with stage, lymph nodes, distant metastases, and worse survival." (PMID 32397382, 2020). "In gastric cancers, HOTAIR-induced cisplatin resistance is mainly related with the activation of the PI3K/Akt signaling pathways via miR-34a and miR-126, both involved in the modulating the apoptotic process." (PMID 32397382, 2020). "In gastric cancer, HOTAIR expression was higher in tumor when compared with the adjacent noncancerous tissues, and was significantly correlated with lymph node metastasis, TNM stage, and invasion." (PMID 32951010, 2020). "For instance, HOTAIR was considered to play an important role in gastric cancer by PI3K/Akt and Wnt/β-catenin signaling pathways by up-regulating miR-34a." (PMID 32349783, 2020). "In gastric cancer, HOTAIR has been detected in patients’ plasma, and its circulating level is able to predict which patient can benefit from fluorouracil and platinum combination therapy." (PMID 32397382, 2020). "HOTAIR is also upregulated in gastric cancer promoting tumor growth and metastasis and is therefore proposed as biomarker for poor prognosis in gastric cancer patients." (PMID 33291485, 2020). "Previous studies have been reported that HOTAIR was negatively correlated with DDP-resistance in gastric cancer, human lung adenocarcinoma, and small cell lung cancer." (PMID 32349783, 2020). "Overexpression of HOTAIR has been shown to promote metastasis, invasiveness of various types of cancer, including gastric cancer." (PMID 33333725, 2020). "For example, via inhibiting miR-217 expression, lncRNA HOTAIR can promote ADR resistance of gastric cancer cells." (PMID 32192494, 2020). "Subsequently, more evidence had been accumulated about the aberrant expression of HOTAIR in various cancers, and the pivotal role in cancer progression and metastasis, such as lung cancer, gastric cancer and hepatocellular cancer." (PMID 32104724, 2020). "Another study showed that lncRNA-HOX antisense intergenic RNA (HOTAIR) was highly expressed in gastric cancer, particularly in the diffuse type." (PMID 32219093, 2020). "The lncRNA HOTAIR promotes gastric cancer progression by sponging miR-331-3p to upregulate HER2 expression." (PMID 32382150, 2020). "In gastric cancer, HOTAIR forms complementary base pairing with miR‐331 and inversely correlates with the occurrence of miR‐331." (PMID 30803129, 2019). "HOTAIR knockdown inhibited DDP resistance by upregulating miR-34a, indicating that the effect of HOTAIR/miR-34a axis on gastric cancer (GC) cells is involved in the PI3K/Akt and Wnt/β-catenin signaling pathways." (PMID 30781524, 2019). "To date, the inverse correlation of the expression levels between HOTAIR and miR‐331, and the involvement of miR‐331 in the post‐transcriptional regulatory network of HOTAIR have been reported for cervical and gastric cancer." (PMID 30803129, 2019). "In gastric cancer (GC), HOTAIR epigenetically silences miR-34a by binding the PRC2 (polycomb repressive complex 2) component EZH2 to promote EMT progression." (PMID 31575017, 2019). "A later study revealed that HOTAIR can also epigenetically regulate the transcription of miRNAs in driving gastric cancer invasion and metastasis, demonstrating that HOTAIR directly represses miR34a by PRC2 recruitment." (PMID 29685978, 2018).
gastric cancer (continued). "miR-34a expression is down-regulated and negatively correlated with HOTAIR expression in gastric cancer tissues." (PMID 29721215, 2018). "Similar to lncRNA700, lncRNA HOTAIR was found to promote gastric cancer progression by acting as a ceRNA for miR-331-3p and thereby increasing HER2 expression." (PMID 30439646, 2018). "HOTAIR is upregulated in many tumors, including breast, esophageal, lung, liver and gastric cancers, where high levels of HOTAIR correlate with tumor invasion, progression, metastasis, and poor prognosis." (PMID 29033906, 2017). "Previous studies have found that over-expression of lncRNA HOTAIR contributed to gastric cancer development and predicted a poor prognosis." (PMID 29113415, 2017). "The top 4 predicted gastric cancer-related lncRNAs, H19, HOTAIR, MEG3, and PVT1 were confirmed by the updates of the LncRNADisease database." (PMID 28963512, 2017). "Our analysis missed some lncRNAs that have reported to be associated with overall survival of gastric cancer patients, such as GAS5 and HOTAIR." (PMID 28841672, 2017). "Our previous studies suggest that HOTAIR contributes to gastric cancer development, and the overexpression of HOTAIR predicts a poor prognosis." (PMID 28209170, 2017). "Among the upregulated lncRNAs in the microarray, we had already validated HOTAIR as having dysregulated expression in gastric cancer in a previous report." (PMID 28077118, 2017). "While HOTAIR promotes cellular invasion and the migration of gastric cancer cells, the downregulation of HOTAIR can reverse the epithelial-mesenchymal transition process." (PMID 28649178, 2017). "The findings of previous studies indicate that HOTAIR also functions as a ceRNA by promoting human epithelial growth factor receptor 2 (HER2) expression by competitively binding to hsa-miR-331-3p during gastric cancer pathogenesis." (PMID 28164117, 2017). "HOTAIR epigenetically silences miR34a by binding with PRC2 to promote the epithelial-to-mesenchymal transition (EMT) in human gastric cancer." (PMID 29221147, 2017). "Our data shown the expression level of HOTAIR was drastically higher in gastric cancer tissues and gastric cancer cell lines (MGC-801, SGC-7901 and HGC-27)." (PMID 27751178, 2016). "HOTAIR expression in gastric cancer tissues was more than 30-fold of that in normal tissues, suggesting that the expression of HOTAIR was upregulated in gastric cancer." (PMID 27751178, 2016). "In the present study, the expression level of HOTAIR was determined by quantitative reverse transcription polymerase chain reaction (qRT-PCR), 20 gastric cancer tissues and 20 normal tissues was included." (PMID 27751178, 2016). "The CCK-8 and colony formation assay was used to identify if the knockdown of HOTAIR have an influence on gastric cancer cell lines." (PMID 27751178, 2016). "Compared with normal tissues, higher expression level of HOTAIR was found in gastric cancer tissues." (PMID 27751178, 2016). "HOTAIR knockdown efficiently inhibits cell proliferation and matrix invasiveness in gastric cancer cells in vitro." (PMID 27686732, 2016). "The expression of HOTAIR between gastric cancer tissues and corresponding normal tissues was identified by qRT-PCR." (PMID 27751178, 2016). "In our previous study, we reported that HOTAIR silencing suppressed invasion/migration in gastric cancer cells." (PMID 27659532, 2016). "It has already been shown, that the expression of HOTAIR is upregulated in gastric cancer tissues compared to adjacent normal tissues." (PMID 27659532, 2016). "Dioscin inhibits proliferation of the three gastric cancer cell lines and decrease HOTAIR expression." (PMID 27751178, 2016). "For example, HOTAIR functions as a competing endogenous RNA to regulate HER2 expression by sponging miR-331-3p in gastric cancer; HOTAIR represses the expression of miR-205 by histone modification in colorectal cancer." (PMID 27895308, 2016).
gastric cancer (continued). "In conclusion, these data showed that the expression of HOTAIR was up regulated in gastric cancer and gastric cancer cell lines." (PMID 27751178, 2016). "To determine the function roles of HOTAIR and dioscin in gastric cancer, siRNA was used to silence HOTAIR expression, and we also found dioscin down regulated the expression of HOTAIR." (PMID 27751178, 2016). "In the present study, the expression level of HOTAIR in gastric cancer and adjacent normal tissues was detected." (PMID 27751178, 2016). "HOTAIR expression is significantly increased in gastric cancer tissues compared with paracancerous tissues." (PMID 27464701, 2016). "HOTAIR expression in gastric cancer cell lines SGC-7901, MGC-803 and HGC-27 were significantly higher than that in noncancerous cancer cell line GES-1." (PMID 27751178, 2016). "HOTAIR expression was significantly higher in the diffuse-type gastric cancer (P=0.048) compared to the intestinal-type gastric cancer." (PMID 26136075, 2015). "Inhibition of HOTAIR in gastric cancer cells leads to EMT process reversal and reduction of invasiveness mediated by the expression of MMP1 and MMP367." (PMID 25859406, 2015). "Additional experiments revealed that HOTAIR knockdown significantly repressed migration, invasion and metastasis both in vitro and in vivo and reversed the gastric cancer cell EMT." (PMID 26136075, 2015). "HOTAIR functions as a competing endogenous RNA to regulate HER2 expression by sponging miR-331-3p in gastric cancer, and is targeted and regulated by miR-141 in human renal carcinoma cells." (PMID 26183397, 2015). "In this study, we found that HOTAIR is more highly expressed in diffuse-type gastric cancer than in intestinal-type gastric cancer and is negatively related to E-cadherin." (PMID 26136075, 2015). "Then we detected miR34a expression in gastric cancer tissues and found that miR34a expression was decreased in tumor tissue and negatively correlated with HOTAIR expression in diffuse and intestinal types (r2=0.857 and 0.702, P<0.001)." (PMID 26136075, 2015). "HOTAIR knockdown induced G0/G1 cell cycle arrest in lung adenocarcinoma cells by increasing p21 expression and inhibited gastric cancer cell invasion by inhibiting HER2." (PMID 25823657, 2015). "To investigate the effect of HOTAIR on the invasion and metastasis of gastric cancer cells, we first examined the expression levels of HOTAIR, miR34a and EMT markers in various cancer cell lines by qRT-PCR." (PMID 26136075, 2015). "HOTAIR overexpression promoted the proliferation, migration and invasion of gastric carcinoma cells, endometrial cancer, lung cancer, renal cell carcinoma (RCC)." (PMID 26172293, 2015). "They grafted gastric cancer cells with increased or suppressed HOTAIR expression into the tail vein or peritoneal cavity of immunodeficient mice." (PMID 25334066, 2014). "In our study, qRT-PCR analysis showed that miR-331-3p/miR-124 expression was inversely correlated with HOTAIR expression in advanced gastric cancer." (PMID 24775712, 2014). "The significant increase of HOTAIR expression in gastric cancer samples prompted us to explore the possible biological significance of HOTAIR in tumorigenesis." (PMID 24775712, 2014). "Taken together, these results indicate that knockdown of HOTAIR suppresses gastric cancer cell proliferation and induces apoptosis in vitro." (PMID 24775712, 2014). "In this study, we report that HOTAIR upregulation is a characteristic molecular change in gastric cancer and investigate the biological roles of HOTAIR on the phenotypes of gastric cancer cells in vitro and in vivo." (PMID 24775712, 2014). "In our study, qRT-PCR analysis showed that miR-331-3p/miR-124 expression was inversely correlated with HOTAIR expression in 20 pairs of advanced gastric cancers." (PMID 24775712, 2014). "The level of HOTAIR expression was determined in 78 paired gastric cancer samples and adjacent, histologically normal tissues by qRT-PCR, and normalized to GAPDH." (PMID 24775712, 2014).